PTGDS (prostaglandin D2 synthase)
Diseases named in the same sentence as PTGDS in open-access papers (continued):
Sharing a sentence is not in itself a finding about the gene and the disease.
glaucoma (3 papers, 2019 to 2023). Increased pressure in the eyeball due to obstruction of the outflow of aqueous humor. "For glaucoma, PTGDS, GSTP1, SPD1, and CST3 were expressed significantly higher in almost all tissues; CRP, ALB, and TTR were markedly increased in the liver; MBP and TF exhibited high expression in the brain." (PMID 37052519, 2023). "ONH‐specific gelsolin (Gene name: GSN), prostaglandin D synthase (Gene name: PTGDS), as well as calponin (Gene name: CNN3) were reported as glaucoma ONH astrocyte markers." (PMID 31470587, 2019).
ovarian carcinoma (3 papers, 2022 to 2024). A malignant neoplasm originating from the surface ovarian epithelium. "PGD2, the protein product of PTGDS, inhibits in vitro and in vivo ovarian cancer cell growth and prolongs the survival time of nude mice in serous ovarian cancer." (PMID 39135097, 2024).
adenoma (2 papers, 2014 to 2022). A neoplasm arising from the epithelium. "In our transgenic mice with PTGDS overproduction and reduced adenoma occurrence, the decrease in numbers of large tumors caused by PTGDS appeared blunted in heterozygous Pparg knockout mice." (PMID 24729479, 2014).
asthma (2 papers, 2024). "For sepsis, CX3CR1, PID1 and PTGDS are strongly associated with immune pathways such as “Allograft rejection” and “Asthma”." (PMID 39763654, 2024).
brain tumor (2 papers, 2021 to 2024). "PTGDS was discovered to be of lower amount in brain tumor samples by six-fold when compared to the control samples." (PMID 34966627, 2021). "The PTGDS protein is also identified as a possible effective biomarker of brain tumors, with the current study vouching for its feasibility." (PMID 34966627, 2021).
COVID-19 (2 papers, 2021 to 2023). A disease caused by infection with severe acute respiratory syndrome coronavirus 2. "The heart may be affected by COVID-19-induced decreased expression of PTGDS, which is involved in the production of prostaglandin D2 necessary for the survival of cardiomyocytes." (PMID 37109540, 2023).
lymphoma (2 papers, 2022 to 2025). A malignant (clonal) proliferation of B- lymphocytes or T- lymphocytes which involves the lymph nodes, bone marrow and/or extranodal sites. "Although the expression of PTGDS was higher in the GCB subtype than that in the non-GCB subtype, PTGDS expression was negative in the normal germinal center, indicating the specific high expression of PTGDS in lymphoma cells." (PMID 34743203, 2022). "Notably, PTGDS inhibition displayed excellent anti-lymphoma effects in vitro and in vivo study, through MYH9-mediated regulation of Wnt–β-catenin–STAT3 signaling." (PMID 34743203, 2022). "Collectively, our observations firstly revealed the high expression and prognostic role of PTGDS in PTCL patients, and targeting PTGDS displayed excellent anti-lymphoma effects and enhanced the drug sensitivity of PTCL cells to Sorafenib in vitro and in vivo." (PMID 39706989, 2025). "The abnormal glycosylation of PTGDS could enhance DLBCL cell proliferation, which might partly account for the oncogenic role of PTGDS in DLBCL and provide potential targets for lymphoma therapy." (PMID 34743203, 2022).
medulloblastoma (2 papers, 2013 to 2017). A malignant, invasive embryonal neoplasm arising from the cerebellum. "The candidate biomarker emerging from said study, prostaglandin D2 synthase, was downregulated in the CSF from 33 children with medulloblastoma (compared with 25 controls), sampled at eight institutions across the USA." (PMID 28526811, 2017). "This demonstrated a sixfold mean reduction in prostaglandin D2 synthase (PGD2S) levels in medulloblastoma patients relative to age-matched controls (p < 0.00001)." (PMID 24400253, 2013).
myocardial infarction (2 papers, 2023 to 2025). Gross necrosis of the myocardium, as a result of interruption of the blood supply to the area, as in coronary thrombosis. "This proteomics study with new cohort validation identifies prostaglandin-H2 D-isomerase (PTGDS) as a potential early diagnostic biomarker for myocardial infarction (MI), including both ST-elevated MI (STEMI) and non–non-ST-elevated MI (NSTEMI)." (PMID 40414290, 2025).
narcolepsy (2 papers, 2013 to 2022). A sleep disorder characterized by a tendency for excessive sleepiness during the day which occurs even after adequate sleep in the nighttime. "Increased levels of PTGDS are observed in patients with narcolepsy and excessive sleepiness." (PMID 36010675, 2022).
pneumonia (2 papers, 2012 to 2024). An acute, acute and chronic, or chronic inflammation focally or diffusely affecting the lung parenchyma, caused by an infection in one or both of the lungs (by bacteria, viruses, fungi, or mycoplasma.). "Recent studies indicate that PTGDS possesses anti-inflammatory and pro-resolving characteristics, and its increased expression offers protection against pneumonia caused by Pseudomonas aeruginosa, suggesting that PTGDS is crucial in innate immune reactions." (PMID 39763654, 2024).
testis cancer (2 papers, 2013 to 2024). "Additionally, PTGDS is involved in the regulation of migration and invasion in testicular cancer cells." (PMID 39355132, 2024). "The facts that the increase in PGD2 production and SOX9 expression through PTGDS activation in H-rev107 and RIG1 transfected NT2/D1 cells shown in this and our previous studies support pro-differentiation activities of both RIG1 and H-rev107 in testis cancer cells." (PMID 23687991, 2013).
bipolar disorder (1 paper, 2019). A disorder of the brain that causes unusual shifts in mood, energy, activity levels and the ability to carry out day-to-day tasks. "Another study suggests that dysregulated PTGDS mRNA expression is associated with rapid-cycling bipolar depression." (PMID 30782214, 2019). "Increased PTGDS expression has been shown in patients having attention deficit hyperactivity disorder, compared with patients having bipolar disorder." (PMID 30782214, 2019).
Cachexia (1 paper, 2020). Severe weight loss, wasting of muscle, loss of appetite, and general debility related to a chronic disease. "Genes for both PTGDS and ADORA1 tended to be up‐regulated in association with cachexia, suggesting increased production of prostaglandin D2 that exerted antilipolytic effect, in concert with ADORA1 stimulation." (PMID 33084249, 2020).
cholangiocarcinoma (1 paper, 2025). A carcinoma that arises from the intrahepatic biliary tree (intrahepatic cholangiocarcinoma) or from the junction, or adjacent to the junction, of the right and left hepatic ducts (hilar cholangiocarcinoma). "This revealed tumor‐specific potential markers, several of which have been previously implicated in tumor biology (e.g., F2RL2 in gynecological cancers, DHCR24 and RAG1 in thymic carcinoma, PTGDS in cholangiocarcinoma)." (PMID 40784724, 2025).
coronary atherosclerosis (1 paper, 2022). Atherosclerosis of the coronary vasculature. "The progression of coronary atherosclerosis may be influenced by genes such as PTGDS and DGKE." (PMID 36088434, 2022).
Duchenne muscular dystrophy (1 paper, 2025). Duchenne muscular dystrophy (DMD) is a neuromuscular disease characterized by rapidly progressive muscle weakness and wasting due to degeneration of skeletal, smooth and cardiac muscle. "• Novel therapeutic approach: PK007 is a selective hematopoietic prostaglandin D2 synthase (HPGDS) inhibitor targeting Duchenne Muscular Dystrophy (DMD)." (PMID 40275384, 2025).
Erythema (1 paper, 2025). Redness of the skin, caused by hyperemia of the capillaries in the lower layers of the skin. "Moreover, fibroblasts regulate prostaglandin D2 synthesis via prostaglandin D2 synthase (PTGDS), contributing to vasodilation and the erythema commonly observed in demodectic lesions." (PMID 40718180, 2025).
focal segmental glomerulosclerosis (1 paper, 2023). A renal disorder characterized by sclerotic lesions in the glomeruli. "The glomerular transcriptome sequencing of various glomerular diseases, including membranous nephropathy (MN), focal segmental glomerulosclerosis (FSGS), and minimal change disease (MCD) confirmed that the transcriptional level of PTGDS was significantly decreased." (PMID 37908345, 2023).
lung adenocarcinoma (1 paper, 2025). A carcinoma that arises from the lung and is characterized by the presence of malignant glandular epithelial cells. "PTGDS overexpression decreased the invasiveness of lung adenocarcinoma cells via the regulation of MAPK signal pathway." (PMID 39706989, 2025).
myopia (1 paper, 2017). "Such expression changes were evident, particularly in the late myopia dataset where a wide range of genes linked with oxidative stress were either up-regulated (GPX1, GSTA3, MT-4, APOA1, OTUB, PTGDS, HSPB1, HSPB2) or down-regulated (XHD, SLC40A1, TF, SOD3, HPGDS, BCMO1)." (PMID 28852117, 2017).
neuroblastoma (1 paper, 2026). Neuroblastoma (NB) is the most common solid, extracranial childhood tumor. "Six of these genes (CMBL, LY6E, KLRB1, CTSH, CD3D, and PTGDS) were utilized to construct a risk-scoring model that effectively stratified neuroblastoma patients into high- and low-risk groups with significantly distinct clinical outcomes (p < 0.001)." (PMID 41993132, 2026).
oligospermia (1 paper, 2024). Decreased number of spermatozoa in the semen. "In 1975, Olsson and his research team observed a significant decline in PTGDS concentration in the seminal plasma of patients with oligospermia." (PMID 38858789, 2024).
sarcoidosis (1 paper, 2024). Sarcoidosis is a multisystemic disorder of unknown cause characterized by the formation of immune granulomas in involved organs. "In contrast, both Mac 1 and Mac 2 in sarcoid granulomas adopted an inflammatory state with sarcoidosis-specific gene activation, including CHIT1, PTGDS, and PLA2G7." (PMID 39225100, 2024).
sarcopenia (1 paper, 2024). Progressive decline in muscle mass due to aging which results in decreased functional capacity of muscles. "Our study investigated the plasma proteome of individuals with age-related sarcopenia and identified 8 DEPs that showed promising predictive performance, including IGFBP2, PON3, LRG1, PRDX6, PTGDS, CD163, PRG4, and TRAJ17." (PMID 39725826, 2024).
Sepsis (1 paper, 2024). Sepsis is defined as life-threatening organ dysfunction caused by a dysregulated host response to infection. "This study identified three molecular signatures (CX3CR1, PID1 and PTGDS) linked to the diagnosis and poor prognosis of sepsis and ARDS, validated by RT-qPCR and H&E staining in both patient and mouse samples." (PMID 39763654, 2024). "Our research revealed that reduced PTGDS levels are linked to poor outcomes in sepsis and ARDS." (PMID 39763654, 2024). "Moreover, GSEA analysis results show that PTGDS is implicated in the regulation of glycosaminoglycan degradation, highlighting its potential for preserving vascular integrity and mitigating inflammatory damage during sepsis." (PMID 39763654, 2024). "A predictive model for sepsis was created using three crucial genes—CX3CR1, PID1, and PTGDS—to enhance diagnostic precision." (PMID 39763654, 2024). "Combining the findings from both algorithms and WGCNA, three shared biomarkers (CX3CR1, PID1 and PTGDS) were discovered for both the sepsis and ARDS groups." (PMID 39763654, 2024). "This research is unique due to the combination of various machine learning techniques, which systematically identifying three hub genes (CX3CR1, PID1 and PTGDS) as possible biomarkers for diagnosing and predicting outcomes in sepsis and ARDS." (PMID 39763654, 2024). "In this study, differential gene analysis, WGCNA, and machine learning were utilized to identify novel gene signatures related to sepsis and ARDS (CX3CR1, PID1, and PTGDS)." (PMID 39763654, 2024). "We categorized the sepsis dataset by patient survival outcomes and examined the mRNA expression levels of the genes CX3CR1, PID1, and PTGDS." (PMID 39763654, 2024).
Thyroid deficiency (1 paper, 2023). "Thyroid deficiency has also been reported to affect the expression and activity of prostaglandin D2 synthase, which may alter key brain processes such as myelination and other neuromodulating functions in the CNS." (PMID 38130289, 2023).
vitiligo (1 paper, 2025). Generalized well circumscribed patches of leukoderma that are generally distributed over symmetric body locations and is due to autoimmune destruction of melanocytes. "In conclusion, PTGDS, PNPLA8, and MGLL were implicated in AAM to influence the pathogenesis of vitiligo." (PMID 40078960, 2025). "In this study, we first obtained six AAM-RGs in vitiligo by searching the transcriptome dataset in the GEO database along with difference analysis and machine learning; then, PTGDS, PNPLA8, and MGLL were verified as the three key genes through the validation set." (PMID 40078960, 2025). "In addition, the change in PTGDS expression may affect the normal functions of cells by regulating the oxidative stress level, which is related to the pathogenesis of vitiligo." (PMID 40078960, 2025). "Therefore, PTGDS may play a role in the immunomodulatory mechanism of vitiligo through its metabolite PGD2." (PMID 40078960, 2025). "The RT-PCR results showed that compared with the control group, the expressions of PTGDS and MGLL in the skin tissues of vitiligo patients were significantly downregulated, whereas the expression of PNPLA8 was significantly upregulated." (PMID 40078960, 2025).
tumor (57 papers, 2013 to 2025). "Previous studies have shown that L-PGDS (encoded by PTGDS) decreases proportionally with tumor progression." (PMID 40474982, 2025). "Gene ontology (GO) analysis based on differentially expressed genes revealed that targeting inhibition of PTGDS was closely associated with tumor biology in PTCL cells, including cell death, cell apoptosis, cell cycle, cell aging, autophagy and so on." (PMID 39706989, 2025). "Our study revealed that the higher number of seeding locations (≥ 3) was associated with PTGDS downregulation in both the tumor and stromal regions in the eight internal HGSOC samples and the 40 public HGSOC TCIA and TCGA samples." (PMID 39135097, 2024). "Previous investigations have implicated that PTGDS influenced tumor progression by modulating PPARγ, MAPK, and STAT3 pathways." (PMID 34743203, 2022). "Besides, the regulatory role of targeting PTGDS on the expression of autophagy-associated proteins was confirmed in tumor tissue from mouse models." (PMID 39706989, 2025). "The decreased expression of PTGDS was associated with TNM stage and worse prognosis in tumor patients." (PMID 39706989, 2025). "PTGDS has been found to serve as critical regulator in tumor development by regulating multiple signaling pathways and complex regulatory networks." (PMID 39706989, 2025). "To investigate the clinical association of PTGDS in PTCL patients, we performed further analysis and found that the high expression of PTGDS in tumor tissue was statistically correlated with ALK+ ALCL (p = 0.008) and elevated ESR (p = 0.004) in PTCL patients." (PMID 39706989, 2025). "As a key enzyme in prostaglandin metabolism, PTGDS has been identified as potential prognostic biomarker and important regulator in tumor development." (PMID 39706989, 2025). "In our study, HMOX1 was found to interact with PTGDS and mediate the tumor promoting role of PTGDS in PTCL through promoting iron metabolism and autophagy-dependent ferroptosis." (PMID 39706989, 2025). "In tumor tissues, venous endothelial cells exhibited higher expression of metabolism-related genes such as CYP1B1 and PTGDS, the heightened expression of these genes was associated with poorer prognostic outcomes." (PMID 38414015, 2024). "Through its interaction with MYH9, PTGDS modulates the Wnt signaling pathway and exerts a pro-tumor effect." (PMID 39355132, 2024). "Intriguingly, both POSTN+ and PTGDS + CAFs were detected around the tumor islands, suggesting that these CAFs correspond to the mCAFs in our study as we used COL11A1 and PTGDS to localize them in the tissue." (PMID 39516494, 2024). "Compared to normal tissues, significantly higher expression for SKAP1, LAT and lower expression for CD1D, CD79B, CETP, PTGDS was found in tumor tissues in the TCGA-BRCA cohort." (PMID 37598257, 2023). "Our study in the DLBCL xenograft model also indicated the inhibitory effect of PTGDS inhibition on tumor progression." (PMID 34743203, 2022). "Gene ontology (GO) analysis revealed that PTGDS was closely related to biological processes involved in tumor progression, such as cell proliferation, apoptosis, migration, and so on." (PMID 34743203, 2022). "Tumor-accelerated responses were activated by evading anti-growth signaling with the down-regulation of prostaglandin D2 synthase." (PMID 35328637, 2022). "Limited researches demonstrated that PTGDS was overexpressed in some solid tumors, and its expression was correlated with advanced tumor stages, tumor metastasis, and poor prognosis." (PMID 34743203, 2022). "The tumor-suppressed response was activated by the activation of evading anti-growth signaling via the up-regulation of prostaglandin D2 synthase in prostanoid biosynthesis." (PMID 35328637, 2022). "Our study found that high expression of PTGDS protein in DLBCL was associated with worse prognosis and the inhibited tumor growth by PTGDS knockdown and AT56 supported the oncogenic role of PTGDS in DLBCL." (PMID 34743203, 2022).